ENDOV (endonuclease V)
Description:
[Isoform 1]: Endoribonuclease that specifically cleaves inosine-containing RNAs: cleaves RNA at the second phosphodiester bond 3' to inosine. Active against both single-stranded and double-stranded RNAs. Has strong preference for single-stranded RNAs (ssRNAs) toward double-stranded RNAs (dsRNAs). Cleaves mRNAs and tRNAs containing inosine. Also able to cleave structure-specific dsRNA substrates containing the specific sites 5'-IIUI-3' and 5'-UIUU-3'. Inosine is present in a number of RNAs following editing; the function of inosine-specific endoribonuclease is still unclear: it could either play a regulatory role in edited RNAs, or be involved in antiviral response by removing the hyperedited long viral dsRNA genome that has undergone A- to-I editing (Probable). Binds branched DNA structures. [Isoform 6]: Endoribonuclease that specifically cleaves inosine-containing RNAs: cleaves RNA at the second phosphodiester bond 3' to inosine. Active against both single-stranded and double-stranded RNAs. Cleaves tRNAs containing inosine. [Isoform 7]: Endoribonuclease that specifically cleaves inosine-containing RNAs: cleaves RNA at the second phosphodiester bond 3' to inosine. Active against both single-stranded and double-stranded RNAs. Cleaves tRNAs containing inosine.
Synonyms: FLJ35220
Tractability: PROTAC: ubiquitination databases record sites on it.
Gene: Protein-coding gene on chromosome 17 (80,415,158 to 80,438,086, forward strand). Ensembl gene ENSG00000173818.
Subcellular location: Cytoplasm (Isoform 1); Nucleus, nucleolus; Cytoplasm, Stress granule; Cytoplasm (Isoform 6); Cytoplasm (Isoform 7)
Gene Ontology:
Molecular function: DNA binding; DNA endonuclease activity, producing 5'-phosphomonoesters; protein binding; RNA endonuclease activity producing 5'-phosphomonoesters, hydrolytic mechanism; single-stranded RNA binding; magnesium ion binding; endonuclease activity; hydrolase activity, acting on ester bonds
Cellular component: cytoplasm; nucleolus; cytoplasmic stress granule
Genetic constraint (gnomAD): Loss-of-function variants: 37 observed, 33.83 expected, observed/expected ratio (o/e) 1.09, 90% interval 0.84 to 1.44. The synonymous counts are far from expectation, so gnomAD's model fits this gene poorly and the ratio says little. Missense variants: 441 observed, 333.45 expected, observed/expected ratio (o/e) 1.32, 90% interval 1.22 to 1.43. Synonymous variants: 186 observed, 143.53 expected, observed/expected ratio (o/e) 1.3, 90% interval 1.15 to 1.46.
Homologues: Orthologues: chimpanzee ENDOV (99% identical), mouse Endov (80% identical), pig ENDOV (79% identical), rat Endov (78% identical), dog ENDOV (76% identical), guinea pig ENDOV (70% identical), rabbit ENDOV (57% identical), tropical clawed frog endov (52% identical).
Diseases named in the same sentence as ENDOV in open-access papers:
ENDOV is named in the same sentence as 9 diseases in open-access papers, as found by Europe PMC text mining. Sharing a sentence is not in itself a finding about the gene and the disease. The quoted sentences say what the papers report.
basal cell carcinoma (1 paper, 2020). A carcinoma involving the basal cells. "Clinical trials with the use of topically applied liposomal formulation with bacteriophage T4 CPD damage removal enzyme – T4 endonuclease V resulted in lowered actinic keratoses and basal-cell carcinoma incidence in XP-patients." (PMID 33019598, 2020).
breast carcinoma (1 paper, 2022). "In total, 11 DNA repair genes (UBE2A, RBBP8,RAD50, FAAP20, RPA3, ENDOV, DDB2, UBE2V2,MRE11, RRM2B, andPARP3) were preserved as prognostic genes to estimate risk score, which was applied to establish the prognostic model and stratified breast cancer patients into two groups with high or low risk." (PMID 36713553, 2022). "A total of 11 DNA repair genes, namely, UBE2A, RBBP8,RAD50, FAAP20, RPA3, ENDOV, DDB2, UBE2V2,MRE11, RRM2B, andPARP3, were involved in the prognostic model for breast cancer patients." (PMID 36713553, 2022). "The hazard ratio of five genes (RBBP8,PARP3, ENDOV, UBE2V2, and DDB2) was <1, which plays a protective role in developing breast cancer." (PMID 36713553, 2022).
Headache (1 paper, 2023). Cephalgia, or pain sensed in various parts of the head, not confined to the area of distribution of any nerve. "Combining results from GWAS and FUMA together, we highlighted the role of RNF213 gene and ENDOV gene play in the biological mechanism of broadly defined headache." (PMID 37288313, 2023). "For broadly defined headache phenotype, we identified a locus on Chromosome 17, with the lead single-nucleotide polymorphism rs8072917 (odds ratio 1.08, P = 4.49 × 10−8), mapped to two protein-coding genes RNF213 and ENDOV." (PMID 37288313, 2023). "Among broadly defined headache phenotype, rs8072917 reached genome-wide statistical significance, and this SNP is in cis-acting regulatory elements of the RNF213 and ENDOV gene." (PMID 37288313, 2023).
lung carcinoma (1 paper, 2023). "Indeed, RT–PCR results indicated that the deletion of MEN1 in lung cancer cells increased the instances of short splicing isoforms in the FAM189B, NUBP2, ENDOV and TARBP2 genes, but inhibited generation of the CPSF7, MRRF and LETMD1 splicing isoforms." (PMID 37395406, 2023).
skin disorder (1 paper, 2022). Any deviation from the normal structure or function of the skin or subcutaneous tissue that is manifested by a characteristic set of symptoms and signs. "The use of recombinant liposomal encapsulated T4 endonuclease V and topical DNA repair enzymes in XP-related skin disorders have been proven to be useful but are expensive in practical usage." (PMID 35855222, 2022).
ENDOV also shares sentences with these, for which no sentence is quoted: tumor (2 papers); carotid atherosclerosis (1); glioblastoma (1); ischemic stroke (1).